TNF (tumor necrosis factor)
Diseases named in the same sentence as TNF in open-access papers (continued):
Sharing a sentence is not in itself a finding about the gene and the disease.
Sepsis (continued). "Sepsis sera contained higher levels of TNF-α, IL-6, IL-10 and VEGF compared to controls." (PMID 28086962, 2017). "All that indicated, as sepsis developing, TNF-α levels first elevate and then decreased rapidly." (PMID 28947753, 2017). "Defective TNF-α production is a major trait of sepsis-induced immunosuppression." (PMID 28274246, 2017). "Impaired immune response in sepsis, often described as endotoxin tolerance, is characterized by unresponsiveness of monocytes on lipopolysaccharide (LPS) stimulation to release tumor necrosis factor α (TNFα)." (PMID 28771573, 2017). "During sepsis, pro‐inflammatory cytokines such as tumour necrosis factor (TNF)‐α, interleukin (IL)‐1β, IL‐6 and IL‐17 and bacterial products could up‐regulate the level of G‐CSF which promotes both the generation of both mature and immature neutrophils." (PMID 28244690, 2017). "Furthermore, sepsis sera compared to healthy sera contained higher levels of TNF-α, IL-6, IL-10 and VEGF but a lower concentration of EGF." (PMID 28086962, 2017). "Moreover, the model confirms the low production of TNFα and increased levels of C–C motif ligand 2 when monocytes exhibit a tolerant state similar to that of patients with sepsis." (PMID 28824640, 2017). "On the one hand, in some studies was found that SP could play a role in the inflammatory response to sepsis by the release of pro-inflammatory cytokines as IL-1, IL-6, and TNF-α." (PMID 28714876, 2017). "Furthermore, TNF-α has been reported to play a major role in the early phase of sepsis, as it coordinates the immune system to delay human blood neutrophil apoptosis indirectly by upregulating proinflammatory cytokines such as interleukin-8." (PMID 28067837, 2017). "Besides, as a retrospective study, blood sample was limited to examine other known biomarkers of sepsis-induced immunosuppression, such as monocyte HLA-DR expression, PD-1 on T cells, TNF levels." (PMID 28628675, 2017). "Importantly HLA-DR is best characterized as a phenotypic marker for severity in sepsis linking the innate with adaptive immunity, whereas TNFα secretion reflects an actual cell function." (PMID 28771573, 2017). "Mean plasma levels of TNF-α were above the normal range (0.5–2.8 pg/ml) whilst the whole course of sepsis with a peak at day 0 (11 ± 5 pg/ml), followed by a decrease on day 2 (8 ± 5 pg/ml; P = 0.001) and day 5 (6 ± 3 pg/ml; P = 0.007), proceeding constantly until day 10 (6 ± 5 pg/ml; n." (PMID 28542386, 2017). "One may argue that this is an attempt to combine a functional test with a phenotypic immunological marker in sepsis: Measuring both parameters i.e. TNFα release and HLA levels may improve robustness of monitoring immunoparalysis in sepsis." (PMID 28771573, 2017). "Although IL-6 has both anti- and proinflammatory properties and its systemic levels increased after moderate exercise, the response of this specific cytokine to sepsis or regular exercise differed from the increase in TNF-α, which sustained the OTR/down-induced inflammatory status." (PMID 29163473, 2017). "The findings approve the close interaction between TNF-α and ET-1 in sepsis." (PMID 28542386, 2017). "TNFα is implicated in the pathophysiology of several equine inflammatory disorders including dysregulated immune responses in systemic inflammatory response syndrome (SIRS), sepsis, equine asthma syndrome, and in some experimental models of equine laminitis." (PMID 29034249, 2017). "During late sepsis, however, TNFα significantly decreasedin both wild-type and knockout mice." (PMID 29204146, 2017). "There is a significant body of evidence that concentration of TNF-α and IL-6 is increased in BALF of patients with ARDS, and the persistent elevation of pro-inflammatory cytokines has been associated with a worse outcome in patients with ARDS or sepsis." (PMID 28486961, 2017).
Sepsis (continued). "Treatment with r-hLf decreased the clinical sepsis illness and bacterial loads in the kidney and blood while in vitro assays in macrophage cultures showed that levels of nitric oxide, TNFα and NF-κB expression elicited by LPS were even higher following the addition of r-hLf." (PMID 28257033, 2017). "IL10/TNF ratio increased progressively in patients with increasing sepsis severity and mortality." (PMID 31058274, 2017). "Among the 5 patients who died with sepsis, 4 were on an anti-TNF at the time of death." (PMID 28834898, 2017). "In the experiment involving a CLP model of polymicrobial sepsis in mice, they demonstrated a higher efficacy of the cultured (apoptotic) MSC compared to standard cultures in terms of a decrease in TNF-α and serum creatinine levels after 72 hours from sepsis induction." (PMID 29098010, 2017). "Mitochondrial function depends on TNF, and it has, as we have reviewed, homeostatic effects on the normal reproduction rate of various progenitor cells, of particular clinical importance those of endothelial cells in severe malaria and sepsis." (PMID 28451786, 2017). "Our findings demonstrated that WK2-16 attenuated both the circulating IL-6 and TNF-α levels in the early stage of sepsis, implying that it could be used as a potential and attenuative therapeutic agent in sepsis." (PMID 28661460, 2017). "This study demonstrates an association between significant cardiac depression by SE and increase in expression of pro-inflammatory cytokines (TNF-α, IL-6, and IL-1β) further supporting the current literature regarding the role of pro-inflammatory cytokines in the development of myopathy in sepsis." (PMID 28405943, 2017). "Sera collected on day four from patients with severe sepsis harbored significantly higher concentrations of TNF-α (5.7 vs. 0.7 pg/ml, P < 0.001), IL-6 (24.8 vs. 3.8 pg/ml, P < 0.001), and IL-10 (30.0 vs. 11.9 pg/ml, P = 0.040) than sera collected from healthy controls." (PMID 28086962, 2017). "Plasma samples from sepsis patients differed substantially in their potential to induce endothelial activation and monocyte adhesion despite their almost identical interleukin-6 and tumor necrosis factor-alpha levels." (PMID 27503310, 2016). "Proinflammatory cytokines TNF-α, IL-1β, and IL-6 are produced in the initial phase of sepsis." (PMID 27195281, 2016). "Our findings may also be in line with previous observations of higher plasma levels of type II PLA2 in sepsis patients, which significantly correlated with TNF-α, IL-6 and IL-8 levels." (PMID 26927094, 2016). "The decreased production of TNF may be related to the hyporesponsiveness of PBMCs from patients with severe sepsis or the increased production of an immunosuppressive cytokine such as IL-10." (PMID 27441846, 2016). "While increased TNF production might augment protective host defense mechanisms during infection, increased soluble TNF receptor levels could reduce the deleterious effects of excessive TNF production during sepsis." (PMID 27306751, 2016). "In addition, IL-6, IL-1β, and TNF-α had a central role in activating cytokine cascade response in sepsis and partly involved in pathogenesis of MOF." (PMID 28042205, 2016). "We assessed expression of a panel of genes reported to be highly upregulated during CLP sepsis, including tnfa (tumor necrosis factor α) and il1b (interleukin 1 beta), which were undetectable in the CNS in any condition despite marked upregulation in the liver following CLP (data not shown)." (PMID 26790027, 2016). "Notably, one study showedthat DEX decreased the inflammatory response in ICU patients with severe sepsis morethan did propofol infusion, when TNF-α,IL-1, and IL-6 were used as endpoints of inflammation." (PMID 26909786, 2016). "Rhein could significantly decrease concentration of serum urea and creatinine and level of TNFα, NFκB, and IL-1β in two different mouse models of experimental sepsis." (PMID 26904117, 2016).
Sepsis (continued). "Moreover, sepsis-induced high bacteremia and an intense systemic inflammatory response characterized by elevated serum concentrations of TNF-α, CK-MB, BUN and AST and increased neutrophil accumulation in the lungs, indicated by increased MPO activity." (PMID 26849138, 2016). "In addition to inflammatory cytokines (TNF-α, IL-1 and so on), HMGB1 has recently been shown to mediate the lethal late phase of sepsis and caused coagulopathy." (PMID 27011792, 2016). "On the other hand, Bz was shown to attenuate sepsis-induced TNF overproduction." (PMID 27161638, 2016). "Among the pro-inflammatory cytokines, tumor necrosis factor alpha (TNFα) and interleukin 1beta (IL-1β) are detected in the blood of patients with sepsis and are known to induce septic shock-like conditions when administered to animals in vivo, thus suggesting their key pathogenic roles in sepsis." (PMID 29259697, 2016). "Little data exists comparing the ability of the two most well-studied markers of sepsis-induced immunosuppression, human leukocyte antigen (HLA)-DR expression and lipopolysaccharide (LPS)-induced tumor necrosis factor alpha (TNF-ɑ) production, to predict mortality and morbidity." (PMID 27760554, 2016). "A higher level of TNF-α was observed in sepsis patients compared to SIRS or control groups." (PMID 28469676, 2016). "Finally, miR-23b was reported to play an important role in progression of sepsis by inhibiting the expression of NF-κB, TNF-α, IL-6, ICAM-1, E-selectin, and VCAM-1." (PMID 26761003, 2016). "Our data suggest that mild zinc deficiency increases TNF‐α in muscle acutely after sepsis but does not significantly modulate the rate of muscle protein synthesis." (PMID 27811170, 2016). "Anemia in sepsis is observed frequently and has a multifactorial etiology, including a decrease in production of erythropoietin due to inflammatory cytokines release, such as tumor necrosis factor (TNF-α), interleukin-1 (IL-1), and interleukin-6 (IL-6)." (PMID 27737630, 2016). "Besides the EE increases the survival of animals submitted to the lethal sepsis, activity possibly related to a decrease in TNF-α and IL-6 production and a consequent inhibition of systemic inflammation." (PMID 27630733, 2016). "Similarly, TNF-α production differed among healthy volunteers, severe sepsis patients and septic shock patients in all conditions tested (P < 0.05, Kruskal-Wallis)." (PMID 26879814, 2016). "Furthermore, the sepsis-induced increases in tissue levels of IL-1β, IL-6, and TNF-α mRNAs were lowered when the two blockers were given together to the animals." (PMID 27822777, 2016). "Thus, we evaluated monocyte modulation during sepsis by simultaneously assessing their phagocytic activity, the generation of ROS and NO, and the production of inflammatory cytokines (IL-6 and TNF-α)." (PMID 26879814, 2016). "Since transfection of let-7b-5p mimic could suppress IL-6 and TNF-α production of CB monocytes, regulation of let-7b-5p has the potential to play a role in neonatal sepsis control." (PMID 28066425, 2016). "We evaluated the modulation of monocyte functions during sepsis by simultaneously assessing their phagocytic activity, the generation of reactive oxygen species (ROS) and nitric oxide (NO), and the production of inflammatory cytokines (IL-6 and TNF-α)." (PMID 26879814, 2016). "It was previously found that TNF-α played a pivotal in sepsis which could initiate systematic inflammatory response." (PMID 28042205, 2016). "TNF-α, IL-6, and IL-1β are the main inflammatory cytokines released in sepsis, which may assess the severity of sepsis." (PMID 26904148, 2016). "The activities of complexes I and II of the mitochondrial respiratory chain are diminished in hearts from animals with sepsis, and this might be due to the detrimental effects of sepsis mediators such as NO, TNF-α, IL-1β, and others." (PMID 27011791, 2016).
Sepsis (continued). "The limitations placed on study power by multiple-association testing may in part account for our failure to replicate well-validated correlates of mortality in sepsis (in particular, TNF, IL-6, and IL-10)." (PMID 27170644, 2016). "This failure may beexplained by the fact that the levels of TNF-α and IL-1β are elevated during the earlystage of sepsis and recover at the late stage of disease." (PMID 26648090, 2016). "Given the important role of TNF-α in sepsis such suppression by combination therapy could be a therapeutic effect." (PMID 27932936, 2016). "In the present study, we investigated naringin’s mechanism of action and its inhibitory effect on lipopolysaccharide-induced tumor necrosis factor-alpha and high-mobility group box 1 expression in macrophages, and on death in a cecal ligation and puncture induced mouse model of sepsis." (PMID 27716835, 2016). "Cytokines (TNF-α and IL-1β) might play key roles in the early decrease in contractility, but they cannot explain the prolonged myocardial dysfunction in sepsis because the effect of TNF-α is maximal between 8 and 48 h after administration." (PMID 27011791, 2016). "Corresponding to the enhanced LPS-stimulated TNFα/nitrite production, the significantly up-regulated NFκBp65, p-iNOS and p38MAPα mRNA and protein expressions were found on cultured monocyte of TLR4+896A/G variant allele carriers and severe sepsis cases." (PMID 27861595, 2016). "Besides, pentoxifylline is considered as a favorable medication for patients with sepsis complications due to its anti-tumor necrosis factor (anti-TNF) and antioxidant effects, thus alleviating hepatorenal syndrome." (PMID 27043533, 2016). "Proinflammatory cytokines such as TNF-α, IL-6, IL-1, and IFN-γ play an important role during the course of sepsis, interfering with the prognosis, progression, and intensity of tissue damage, and are associated with the aggravation and lethality of sepsis." (PMID 27630733, 2016). "On the other hand, in patients suffering from sepsis who have entered the immnosuppressive state of the disorder—as identified by reduced HLA-DR expression and by diminished ex vivo LPS-driven TNF-α production—administration of GM-CSF led to a restoration of the monocyte function." (PMID 27695085, 2016). "The animals 18 h after CLP-induced sepsis had marked elevations in IL-1β, IL-6, TNF-α, and MCP-1." (PMID 27822777, 2016). "Historically, severe systemic inflammation—that is, elevated circulating levels of tumor necrosis factor (TNF), interleukin (IL)-6, granulocyte colony-stimulating factor (G-CSF) and other inflammatory mediators—was thought to play the major role in sepsis-induced organ dysfunction." (PMID 27372077, 2016). "A previous study revealed that over-expression of PPARβ/δ could attenuate gene expression of TNFα, IL-1β and IL-6 in alveolar macrophages and played a protective role in sepsis-induced acute lung injury." (PMID 27023591, 2016). "TNF-alpha levels were determined since they have an important role in the pathogenesis of sepsis." (PMID 25948886, 2015). "TNF-α and IL-6 are important pro-inflammatory cytokines in sepsis." (PMID 25873251, 2015). "These associations support the hypothesis that an increase in levels of IL-β, TNF-α and IL-10 secretion due to genetic variation in their genes may contribute to the development of sepsis after severe trauma by affecting the induced immune response." (PMID 26561011, 2015). "Interestingly, the varied amount of TNF-α in all three groups: healthy controls, non-sepsis and sepsis patients showed an example of expression masking of the genotype with a high producer genotype of IL-10 in these patients." (PMID 26561011, 2015). "GFZ also reduced the sepsis-induced elevations of TNF-α and IL-1." (PMID 25667670, 2015). "Therefore, kallistatin protects against sepsis-induced inflammation, organ damage and mortality by antagonizing TNF-α- and HMGB1-mediated inflammatory gene expression, and by inducing SOCS3 synthesis." (PMID 25930108, 2015).
Sepsis (continued). "Interestingly, the only cytokine which in the logistic regression analysis confirms its significance also after comparison of sepsis only with SIRS patients is TNF-α." (PMID 26635427, 2015). "In the case of sepsis a significant increase of IL-6 (P = 0.0020), IL-8 (P = 0.0020), sIL-2R (P = 0.0156), and TNF-α (P = 0.0078) was observed in all pediatric patients (n = 8) for which an analysis of the cytokine levels was performed on the day of the occurrence of sepsis." (PMID 26315105, 2015). "Furthermore, in animal models, approaches to neutralize TNF have been successful to protect against LPS-induced shock or sepsis." (PMID 26071594, 2015). "Furthermore, in response to ouabain treatment, monocytes from severe sepsis patients produced more TNF-α mRNA (Fig2B) and cytokines (Fig2B) than did monocytes from normal donors." (PMID 25535255, 2015). "Of them, TNF-α is a major cytokine involved in promoting cardiac dysfunction during sepsis." (PMID 26486084, 2015). "Furthermore, 5-HTP given by i.p. injection at 30, 100 and 300 mg/kg was found to decrease the production of TNFα in a sepsis model." (PMID 26669765, 2015). "Additionally, ouabain increased HLA-DRα and HLA-DRβ gene expression and restored TNF-α production in monocytes from sepsis patients." (PMID 25535255, 2015). "However, it has been suggested that doses of 0.3–1 ng/kg body weight which result in a 3–100 fold rise in TNF-α resemble the concentrations during human sepsis more accurately." (PMID 25893426, 2015). "MAPKs are the key transducers for the production of TNF-α in endotoxemia or sepsis." (PMID 26486084, 2015). "TNF-alpha has important roles in the development of organ dysfunction related to sepsis." (PMID 25948886, 2015). "However,TNF-α -238(AA), IL-1α-889(CC) and IL-10-1082(GG) genotypes appeared to be a higher producer by CBA assay, but IL-10 masked the expression of the high producing genotype of TNFα -238(AA) in sepsis patients." (PMID 26561011, 2015). "Thus, CXCL10 in combination with other cytokines such as TNF are potential biomarkers for sepsis as a consequence of pyometra progression and also as targets in anti-inflammatory therapy in pyometra." (PMID 26222498, 2015). "Yet while prior anti-TNF antibody prevented the illness caused by injecting LPS to induce experimental sepsis, it was of no help when administered to mice that had already been made sick by LPS." (PMID 26221543, 2015). "Notably, clinical studies of patients with sepsis indicate that the mortality rates and expression levels of TNF-α are lower in females compared with males." (PMID 25738436, 2015). "TNF was the first cytokine to be detected in the bloodstream of patients with sepsis." (PMID 26071594, 2015). "However, clinical trials with anti-cytokine agents, such as anti-TNF-α antibodies and soluble IL-1 receptor antagonists, have proven ineffective in the treatment of sepsis." (PMID 26579229, 2015). "TNF-α and IL-1β are the most intensively studied inflammatory mediators of pathology in sepsis." (PMID 26440998, 2015). "Therefore, TNF-α has been regarded as the important target for the treatment of endotoxemia or sepsis." (PMID 26486084, 2015). "In doses ranging from 25 to 75 mg/kg body weight, CSL-111 was able to suppress production of pro-inflammatory cytokines TNF-α, IL-6, and IL-8, inhibit sepsis-induced hypotension, and markedly decrease the severity of clinical symptoms when administered prophylactically." (PMID 26557091, 2015). "Rhein could significantly decrease concentration of BUN and SCr and level of TNF-α and IL-1β in two different mouse models of experimental sepsis." (PMID 26149595, 2015). "Despite a ghrelin-induced leptin elevation and the ability of leptin to generally improve cytokine response in sepsis the increase in TNFα with simultaneous IL-10 and IL-1ß decline may be a sign of suppression of an early and effective immune response." (PMID 25844479, 2015).